OSM (oncostatin M)
Diseases named in the same sentence as OSM in open-access papers (continued):
Sharing a sentence is not in itself a finding about the gene and the disease.
brain diseases (1 paper, 2016). "Recent evidence suggest that oncostatin M (OSM), a pleiotropic cytokine belonging to the IL-6 family, might influence neurodegenerative processes associated with a variety of brain diseases." (PMID 27287400, 2016).
genetic diseases (1 paper, 2025). "Thus, despite the description of these genetic diseases and a plethora of studies conducted in various cellular and animal models, the specific function of OSM in vivo has remained elusive, especially in humans." (PMID 39847438, 2025).
neurological diseases (1 paper, 2022). "While AXIN, uPA, OSM and MMP9 may be emerging as potential biomarker targets, their performance and specificity is not yet well understood across multiple populations and neurological diseases." (PMID 35734478, 2022).
retinopathy (1 paper, 2017). "Together, our analysis added new upstream regulators such as oncostatin-M to glycemia-dependent regulators of gene expression changes in experimental retinopathy models." (PMID 28575111, 2017).
OSM also shares sentences with these, for which no sentence is quoted: ulcerative colitis (4 papers); bone marrow failure syndrome (3); colon cancer (3); inflammatory skin disease (3); metabolic syndrome (3); cardiac sarcoidosis (2); cardiomyopathies (2); chronic heart failure (2); depression (2); hematological malignancies (2); lung adenocarcinoma (2); neutropenia (2); steatosis (2); systemic lupus erythematosus (2); acute myeloid leukemia (1); acute respiratory distress syndrome (1); adenocarcinoma (1); adenoma (1); African trypanosomiasis (1); AIDS (1); alcohol use disorder (1); allergic rhinitis (1); Allergy (1); alopecia areata (1); Anxiety (1); aortic stenosis (1); astroglioma (1); autoimmune hepatitis (1); biliary tract neoplasm (1); chronic gastritis (1).
A further 49 diseases each share a sentence with OSM in 1 paper.